CCR2 (C-C motif chemokine receptor 2)
Diseases named in the same sentence as CCR2 in open-access papers (continued):
Sharing a sentence is not in itself a finding about the gene and the disease.
renal fibrosis (continued). "An in-depth study of the role of MCP-1/CCR2 axis in the inflammatory response and complex immune cell signaling network may provide new ideas for treating renal fibrosis, benefiting an increasing number of patients with CKD." (PMID 37861543, 2023). "MCP-1/CCR2 axis seems to play a bridging role in the inflammatory cascade of renal fibrosis." (PMID 37861543, 2023). "To summarize, the MCP-1/CCR2 axis is very important in renal fibrosis." (PMID 37861543, 2023). "However, in contrast to hepatic fibrosis, Notch signal regulates macrophages with distinct mechanisms in renal fibrosis, namely the CCR2-mediated monocyte recruitment and local macrophage activation." (PMID 29644573, 2019). "Finally, we found that myeloid-specific Notch activation aggravated renal fibrosis, which was mediated by CCR2+ macrophages infiltration." (PMID 29644573, 2019). "Indeed, myeloid-specific RBP-J knockout decreased while NIC over-expression increased the number of CCR2+ macrophages in fibrotic kidney, consistent with attenuated or aggravated renal fibrosis in these mice, respectively." (PMID 29644573, 2019). "In this study, we tested the hypothesis that CCR2 participates in the recruitment of fibroblasts into the kidney during the development of renal fibrosis." (PMID 24130892, 2013). "In summary, these data define a novel mechanism by which CCR2 participates in renal fibrosis." (PMID 24130892, 2013). "Targeting the Ccl6/Ccr2 axis may help delay the progression of renal fibrosis post-AKI and provide novel theoretical insights and potential therapeutic targets for mitigating the transition from AKI to CKD and developing anti-fibrotic therapies, pending validation in future functional studies." (PMID 40953007, 2025). "Taken together, our functional studies preliminarily elucidate that the interaction between macrophage derived Ccl6 and Ccr2 facilitates M2 polarization and induces macrophage migration, which may in turn contribute to the progression of renal fibrosis following AKI." (PMID 40953007, 2025). "The MCP-1/CCR2 axis may be harmful or beneficial at different stages of renal fibrosis." (PMID 37861543, 2023). "Thus, the MCP-1/CCR2 axis is also a very important player in chemokine signaling in renal fibrosis." (PMID 38239353, 2023). "We also confirmed that Ccl6+Ccr2+Arg1+ macrophages exhibit increased infiltration at day 7 post-AKI, with their infiltration level positively correlated with the degree of renal fibrosis." (PMID 40953007, 2025). "Collectively, our in vivo findings demonstrate that pharmacological inhibition of Ccr2 reduces macrophage infiltration and M2 marker (Arg1) expression in the kidney 7 days after AKI, as well as ameliorates renal fibrosis." (PMID 40953007, 2025). "Inhibition of Ccr2 in AKI mice reduced the infiltration of Arg1+ macrophages and attenuated the progression of renal fibrosis." (PMID 40953007, 2025). "It is demonstrated that NAFLD exacerbates renal fibrosis, as HFD‐induced hepatocytes release significant levels of ANGPTL8, which activates renal CCR2+PIRB+ macrophages." (PMID 40995682, 2025). "Activated cells produce TGF‐β, IL‐6, and IL‐23, driving Th17 activation and promote the formation of myofibroblasts, while CCR2+PIRB‐ macrophages secrete PDGFB promoting fibroblast proliferation, leading to the exacerbation of renal fibrosis." (PMID 40995682, 2025). "During kidney injury, Ccr2 participates in inducing the migration of monocytes to the site of damage, releasing TGF-β and IL-6, and promoting the progression of renal fibrosis." (PMID 40953007, 2025). "Besides its chemotactic capacity, the MCP-1/CCR2 axis has been associated with the transdifferentiation of macrophages to myofibroblasts in a model of Twist1-deficient mice with UUO in which the levels of MCP-1 and CCR2 and consequently renal fibrosis were reduced." (PMID 39450175, 2024).
renal fibrosis (continued). "Among them, monocyte chemoattractant protein-1 (MCP-1) and C–C chemokine receptor type 2 (CCR2), the main receptors of MCP-1, are widely studied chemokines in renal fibrosis." (PMID 37861543, 2023). "In addition, MCP-1/CCR2 axis may also have a protective effect on renal fibrosis." (PMID 37861543, 2023). "Piezo1 can increase macrophage accumulation by upregulating CCL2, the C-C motif chemokine receptor 2 (CCR2) pathway, and the knockout of Piezo1 in mice can inhibit macrophage infiltration, inflammation, and renal fibrosis." (PMID 37509528, 2023). "It is particularly important to identify the different stages of renal fibrosis and select the timing of targeted therapy, which poses a greater challenge to the targeted MCP-1/CCR2 axis in the treatment of renal fibrosis." (PMID 37861543, 2023). "In a renal fibrosis model, the deletion of transient receptor potential vanilloid type 1 aggravated renal injury in salt-sensitive hypertension by enhancing MCP-1/CCR2 signaling-dependent inflammatory responses." (PMID 27788494, 2016). "In addition, CCR2+PIRB+ macrophages promote the activation and proliferation of Th17 cells, which can further contribute to the worsening of renal fibrosis." (PMID 40995682, 2025). "To explore the regulatory roles of CCR2+PIRB‐ and CCR2+PIRB+ macrophages in renal fibrosis and T‐cell inflammation, we established coculture systems with primary renal macrophages and primary fibroblasts, as well as primary renal macrophages and primary CD4+ T cells." (PMID 40995682, 2025). "CCR2, as the main receptor of MCP-1, is an important chemokine in renal fibrosis." (PMID 38239353, 2023). "Moreover, there are other signal pathways involved in renal fibrosis, and the biological function of MCP-1/CCR2 axis is regulated by various factors." (PMID 37861543, 2023). "Finally, the CCL2-CCR2 axis in macrophages has also been found to be important in renal fibrosis, where mononuclear cell infiltration and expression of chemokine receptors CCR1, CCR2, and CCR5 was enhanced in a spontaneous model of lupus nephritis." (PMID 30245686, 2018). "Consistent with this notion, CCR2 and CCL21/CCR7 have been reported to play a role in the recruitment of bone marrow-derived fibroblast precursors into the kidney and the development of renal fibrosis." (PMID 26941655, 2016). "Given the significant correlation between NAFLD and renal fibrosis, we propose the central hypothesis that ANGPTL8 derived from NAFLD activates the ALOX5AP pathway in renal CCR2+PIRB+ macrophages via PIRB, reprogramming linoleic acid metabolism, and driving profibrotic inflammation." (PMID 40995682, 2025). "By inhibiting the MCP-1/CCR2 axis, NOX-E36 could reduce monocyte recruitment and macrophage infiltration, thereby decreasing monocyte-macrophage-induced matrix deposition and delaying renal fibrosis in DN." (PMID 37861543, 2023).
heart failure (29 papers, 2020 to 2025). Inability of the heart to pump blood at an adequate rate to meet tissue metabolic requirements. "Put another way, the abundance of CCR2+ macrophages in human heart failure was associated with persistent LV systolic dysfunction and adverse ventricular remodelling following mechanical unloading." (PMID 35327464, 2022). "In patients with heart failure, CCR2+ macrophage abundance is associated with left ventricular remodeling and systolic function." (PMID 35360222, 2021). "The CCR2+HLA-DRhi subset displays pro-inflammatory activity, consistent with previous reports associating increased CCR2+ monocyte-derived macrophages with poor prognosis in heart failure." (PMID 40520014, 2025). "Increases were observed in PET signals for CXCR4, a marker of old activated neutrophils that cause tissue damage, and for CCR2 which marks a pro-inflammatory subset of monocytes-macrophages, that associates with adverse left ventricle remodeling and heart failure progression." (PMID 36061565, 2022). "In summary, CCR2+ macrophages play major roles in ventricular remodelling in experimental rodents, and they likely have similar effects in human heart failure." (PMID 35327464, 2022). "While tissue-resident CCR2neg MACs inhibit monocyte recruitment, CCR2+ tissue MACs recruit monocytes and promote cardiac inflammation and contribute to adverse heart remodeling and the pathogenesis of heart failure in humans." (PMID 36061565, 2022). "For instance, the population of proinflammatory CCR2+ macrophages has been suggested as a potential novel target in heart failure treatment." (PMID 34387811, 2022). "The goal is to facilitate research and innovation efforts in heart failure therapeutics by drawing attention to the importance of studying the manner by which CCR2+ macrophages mediate their deleterious effects." (PMID 35327464, 2022). "The CCR2+ macrophage subset was more abundant than the CCR2- subset in heart failure samples from those with worse left ventricular systolic dysfunction and adverse remodeling." (PMID 33708206, 2021). "Analysis of transcript expression in the isolated hearts revealed that transcript expression of the proinflammatory cytokines Il6 and Il1b and the heart failure markers Anf and Bnp were significantly lower in Ccr2-KO mice." (PMID 34315245, 2021). "Among the different immune cell subpopulations that accumulate in the myocardium in response to pathological hemodynamic stress, CCR2+ monocyte-derived macrophages have emerged as central players in adverse ventricular remodeling and the development of heart failure." (PMID 37115698, 2023). "Furthermore, these deleterious effects of CCR2+ macrophages, observed in experimental rodents, seem likely to be replicated in the human heart failure setting." (PMID 35327464, 2022). "Expression of the chemokine receptor CCR2 identifies early infiltrating bone marrow–derived monocytes which differentiate to inflammatory CCR2+ macrophages at the site of infarction, where they aggravate local tissue inflammation contributing to heart failure." (PMID 34196821, 2021). "The authors concluded that the CCR2 siRNA could be useful as a therapeutic tool to reduce left ventricular remodeling and improve post-MI heart failure in animals." (PMID 34302556, 2021). "Careful and selective inhibition of CCR2+ monocytes and macrophages at early stages of cardiac stress decreased pathological hypertrophy, fibrosis, and systolic dysfunction, suggesting that modulating CCR2+ macrophages and monocytes may be critical in avoiding or preventing heart failure." (PMID 40909274, 2025). "As previously discussed, the phenotype of CCR2+ macrophages is altered in abundance in response to pressure overload and play a critical role in the management and progression of pathological conditions, which can result in maladaptive cardiac remodeling and heart failure." (PMID 39682749, 2024).
heart failure (continued). "The recruitment of chemokine CC motif receptor 2 (CCR2)-positive (CCR2+) monocyte/macrophage subset to the injured myocardium was reported to stimulate pro-inflammatory responses, promote collateral tissue damage, and ultimately contribute to adverse remodeling and heart failure pathogenesis." (PMID 35215296, 2022). "Hence, CCR2+ macrophages may promote the progression to heart failure by facilitating the activation and expansion of T cell populations through the presentation of cardiac antigens." (PMID 35327464, 2022). "Lastly, we recognized that CCR2+ cardiac macrophages are not the only immune cells to be implicated in ventricular remodeling; for instance, CD4+ T cells also play an important role in the transition from cardiac hypertrophy to heart failure." (PMID 37115698, 2023). "Therefore, inhibiting the infiltration of CCR2+ cardiac non-resident macrophages and promoting the proliferation and activation of CCR2– cardiac resident macrophages is an important way to prevent excessive cardiac fibrosis, resolve adverse cardiac remodeling and improve heart failure." (PMID 35330948, 2022). "Moreover, a study enrolling patients with severe heart failure suggested a negative correlation between left ventricular ejection fraction (LVEF) and the abundance of CCR2-positive macrophage in the cardiac tissue." (PMID 33048984, 2020). "We were able to show that a lack of CCR2 dependent recruited Ly6Chigh monocytes in the myocardium reveled cardioprotective effects resulting in less hypertrophy and reduced brain natriuretic peptide (BNP) expression, as biomarker of heart failure, in the myocardium." (PMID 40257974, 2025). "Within the Ly6clow group of macrophages that proliferates 1 week after TAC, on the other hand, it is the CCR2+ macrophages that are affected by the absence of CD8+T cells and that produce the growth factors (IGF-1, AREG, OSM) which are supposed to be involved in reduced heart failure." (PMID 34745139, 2021).
influenza infection (29 papers, 2010 to 2025). "Although the loss of CCR2 impairs CD8+ TRM cell accumulation in influenza models, CD4+ TRM cell accumulation after pneumococcal pneumonia did not depend on this chemokine receptor." (PMID 35133985, 2022). "Inflammatory monocytes have been associated with lung damage in severe influenza infection, as CCR2−/− mice have increased lung integrity and greater disease resistance 25, 26, but inflammatory monocytes are required for full adaptive anti-influenza responses." (PMID 26265006, 2015). "We find that upstream of bacterial colonization, inflammatory monocytes and other CCR2-dependent myeloid cells recruited during influenza infection promote susceptibility by compromising lung integrity through a TRAIL-mediated mechanism." (PMID 26265006, 2015). "If accumulation of CCR2+ inflammatory monocytes is a common phenomenon in highly pathogenic influenza infection, CCR2+ inflammatory monocytes will be a good therapeutic target in infection." (PMID 25407417, 2014). "While the level of mononuclear cells was attenuated, greater numbers of neutrophils were found in the BAL of CCR2 deficient smoke-exposed, influenza-infected animals than in wild-type controls." (PMID 20967263, 2010). "While a CCR2 deficiency led to attenuated percentages of tipDCs in influenza-infected mice compared to controls, as previously reported, percentages of CD69+, CD4 and CD8 T cells were significantly attenuated in CCR2 deficient mice." (PMID 20967263, 2010). "Additionally, studies have shown that CCR2 blockade reduces lung pathology associated with influenza infection and partially suppresses the neutrophil response in mice exposed to lethal IAV strains." (PMID 37904257, 2023). "Only deficiencies in MCP-1 receptor (CCR2) or IP-10 were protective during influenza infection." (PMID 31293574, 2019). "In addition, body weight loss and viral titres were unchanged in smoke-exposed influenza-infected CCR2 deficient mice compared to controls." (PMID 20967263, 2010). "Previous studies show that the chemokine receptor CCR2 (the primary receptor for CCL-2) is crucial in severe influenza infection." (PMID 40626651, 2025). "As an example, in a murine post-influenza model of infection, Ccr2-/- mice exhibited significantly higher survival and improved bacterial clearance post MRSA challenge." (PMID 39418302, 2024). "In influenza infections, CCR2+ monocytes are recruited to the lungs and contribute to overwhelming inflammatory responses, leading to worsened disease." (PMID 37965344, 2023). "Studies have also shown that CCR2+ inflammatory monocytes drive lung injury and mortality in juvenile mice during influenza infection, highlighting the detrimental effects of this cell type." (PMID 37965344, 2023). "The role of CCR2 in AM remodeling seems so far to be specific to recovery from influenza infections." (PMID 35133985, 2022). "They demonstrate the utility of this tool by assessing binding of different antibodies to a panel of influenza hemagglutinin antigens and to epitope/domain map CCR2 and CCR5 antibodies." (PMID 34824350, 2021). "To conclude, CCR2 is required for the recruitment into the influenza-infected lung of three closely related myeloid cell types, namely inflammatory monocytes, monocyte-derived DCs and interstitial macrophages." (PMID 26265006, 2015). "In conclusion, in mild influenza infection, we find an almost complete overlap between CCR2 dependency and TRAIL expression among monocyte-derived populations." (PMID 26265006, 2015). "Mice that lack the gene for its receptor on the macrophage cell surface, CCR2, exhibit a significant reduction in macrophage migration to the lung and a lower rate of mortality upon influenza infection." (PMID 26393920, 2015).